HMGB1 (high mobility group box 1)
Diseases named in the same sentence as HMGB1 in open-access papers (continued):
Sharing a sentence is not in itself a finding about the gene and the disease.
kidney damage (22 papers, 2013 to 2026). "FA shields rat kidneys from IR-induced injury by suppressing HMGB1-mediated inflammation and apoptosis, suggesting a potential therapeutic avenue for IR-associated kidney damage." (PMID 38326739, 2024). "The present results suggest the involvement of the β-catenin pathway in aortic calcification and kidney damage associated with HMGB1 release." (PMID 29922171, 2018). "The mechanism by which HMGB1 promotes kidney damage in this setting appears to involve inflammation caused by activation of the innate immune system." (PMID 29844451, 2018). "Higher levels of serum HMGB1 were associated in type 1 diabetes patients with a higher risk of mortality, cardiovascular disease, and kidney damage." (PMID 23772226, 2013). "Studies have reported that HMGB1 inhibitors and HMGB1-neutralizing antibodies are effective in improving kidney function and attenuating kidney damage in various AKI mouse models." (PMID 40709185, 2025). "Following sections provide a comprehensive explanation of the mechanisms by which HMGB1 facilitates drug-induced kidney damage (HMGB1 and Drug-Induced Kidney Injury)." (PMID 39008169, 2024). "By means of the model, our results demonstrate that the amplification of HMGB1 signaling is an important contributor to the worsened kidney damage." (PMID 36448056, 2022). "The RAGE ligand HMGB1 also plays a causal role in renal inflammation by enhancing ERK1/2, TNF-α, interleukin (IL)-6, and MCP-1, leading to nephropathy and chronic kidney disease." (PMID 33568752, 2021). "Cisplatin contributes to HMGB1 release from kidney proximal tubular cells, which results in the promotion of inflammation during kidney damage." (PMID 33126443, 2020). "However, the administration of MAPK/Erk1/2 inhibitor has been shown to avert kidney damage, including decreasing HMGB1 secretion from renal epithelial cells and urine accumulation." (PMID 39008169, 2024). "As for kidney damage after CS, excluding the role of myoglobin to renal tubular obstruction directly, HMGB1 also may contribute to the damage." (PMID 28701229, 2017). "Therefore, AAI‐induced nephropathy may be initiated through HMGB1‐mediated TLR activation." (PMID 35765703, 2022). "Evidence from experimental studies indicates that HMGB1 levels rise significantly in both serum and renal tissues following ischemia-reperfusion injury (IRI) or nephrotoxin exposure, correlating strongly with kidney damage severity." (PMID 40727103, 2025). "Notably, our investigation demonstrated that HMGB1 knockdown correlated with increased Cystatin C levels, typically indicative of low GFR and high kidney damage." (PMID 38187339, 2024). "The present experiment corroborates these claims, and it also implies that QB may be able to inhibit the HMGB1/TLR4/MyD88 pathway, thereby reduce autoantibody production, inhibit the release of inflammatory factors, and improve kidney damage." (PMID 35571092, 2022). "This study aimed to explore the relationship between HMGB1, JNK, and TNF-α in kidney damage." (PMID 28701229, 2017). "HMGB1 from injured muscle activates JNK in the kidneys and JNK enhances production of TNF-α, which in turn enhances the production of JNK, resulting in soaring TNF-α level, which contributes to kidney damage." (PMID 28701229, 2017). "In addition, it is not clear whether administration of anti-TNF-α, anti-HMGB1 antibodies, and SP600125, a JNK inhibitor, exerts a protective effect against TNF-α induced kidney damage." (PMID 28701229, 2017).
malignant mesothelioma (22 papers, 2013 to 2025). A malignant neoplasm of the pleura or peritoneum, arising from mesothelial cells. "Malignant mesothelioma (MM) is a highly aggressive cancer strongly associated with asbestos exposure, and accumulating evidence suggests that high mobility group box 1 (HMGB1) plays a central role in its pathogenesis." (PMID 40559922, 2025). "This has been implicated in the SA-associated attenuation of malignant mesothelioma (MM), whereby HMGB1 has been identified as a critical regulator in the onset and progression of MM." (PMID 39682695, 2024). "Particularly the DAMP-associated protein HMGB1 has been suggested to promote cancer progression in malignant mesothelioma also evidenced by elevated serum levels of malignant mesothelioma patients which indicates a supportive role of DAMPs for CSC functions." (PMID 28148265, 2017). "In the present study, we quantified serum HMGB1 levels in a Chinese AE population and further evaluated the diagnostic value of HMGB1 in patients with nonmalignant and malignant ARDs, including pleural plaques (PP), asbestosis, and malignant mesothelioma (MM)." (PMID 28348451, 2017). "In this work, we detected preoperative serum HMGB1 levels in Chinese asbestos-exposed (AE) and ARDs populations and further evaluated the diagnostic value of HMGB1 in patients with certain types of ARDs, including those with pleural plaques, asbestosis, or malignant mesothelioma (MM)." (PMID 28348451, 2017). "Because ethyl pyruvate successfully decreased RAGE accumulation and the activation of NF-κB, research has discovered that it has a significant role in reducing HMGB1 release in malignant mesothelioma cells." (PMID 36613714, 2022). "Further emphasizing the role of the RAGE–HMGB1 axis in cancer progression, blockade of either HMGB1 or RAGE can reduce malignant mesothelioma and glioma tumour growth and metastasis." (PMID 35344301, 2022). "The authors established that there was a significant impairment of HMGB1 secretion by malignant mesothelioma cells due to ethyl pyruvate, leading to reduction in RAGE expression and NF-κB activation." (PMID 32443845, 2020). "Total HMGB1 was significantly increased in malignant mesothelioma patients and asbestos-exposed individuals compared with healthy controls." (PMID 33299138, 2020). "Others found that both patients with malignant mesothelioma and healthy population exposed to asbestos had higher HMGB1 expression in the serum, but HMGB1 only in patients with malignant mesothelioma are highly acetylated." (PMID 30539006, 2018). "EP impairs HMGB1 secretion by malignant mesothelioma cells and downregulates RAGE expression and NF-κB activation." (PMID 28969092, 2017). "Some cancer cells also have the ability to secrete HMGB1 themselves into the culture media, such as colon cancer and malignant mesothelioma." (PMID 28969092, 2017). "It is reported that HMGB1 releases from human malignant mesothelioma cells and promotes proliferation of these cells via an autocrine circuit." (PMID 28969092, 2017). "High-mobility group box 1 (HMGB1) is an inflammatory molecule that has a critical role in the initiation and progression of malignant mesothelioma (MM)." (PMID 26068794, 2015). "Therefore, the PLF of rats with malignant mesothelioma is expected to contain elevated levels of HMGB1." (PMID 35449069, 2022). "Furthermore, ethyl pyruvate reduced the HMGB1 serum scale in vivo and suppressed the growth of malignant mesothelioma xenografts." (PMID 36613714, 2022). "Moreover, ethyl pyruvate reduced HMGB1 serum levels in mice and inhibited the growth of malignant mesothelioma xenografts." (PMID 32443845, 2020). "As discussed in Section 2.2, inflammation induced by HMGB1 contributes to malignant mesothelioma." (PMID 30891101, 2019). "Notably, hyperacetylated HMGB1 in serum of patients is a definite biomarker to differentiate malignant mesothelioma patients from individuals occupationally exposed to asbestos and unexposed controls." (PMID 30539006, 2018).
malignant mesothelioma (continued). "Treatment with HMGB1 inhibitors prolonged the survival of malignant mesothelioma xenograft mice." (PMID 29868478, 2018). "Furthermore, hyperacetylated HMGB1 is more specific and sensitive serum biomarker to diagnosis of malignant mesothelioma than HMGB1." (PMID 30539006, 2018). "Moreover, EP reduces HMGB1 serum levels in mice and inhibits the growth of malignant mesothelioma xenografts." (PMID 28969092, 2017). "Furthermore in a malignant mesothelioma study, targeting HMGB1 by mAb also showed to effectively inhibit the matrigel invasion of malignant mesothelial cells in vitro, hinder the tumor growth, and extend the survival of nude mice." (PMID 23766911, 2013). "Previous studies have shown that serum HMGB1 can serve as a biomarker for variety of cancers such as pancreatic ductal adenocarcinoma, colorectal carcinoma, malignant mesothelioma, canine lymphoma, non-small-cell lung cancer, gastric cancer, and hepatocellular carcinoma." (PMID 23766911, 2013). "The difference between A549 NSCLC cells and malignant mesothelioma REN and EMMESO cells regarding HMGB1 secretion suggests that different cancer cells will differ in their capacity to secrete HMGB1 in response to cisplatin therapy." (PMID 37759736, 2023).
psoriasis (22 papers, 2017 to 2025). An autoimmune condition characterized by red, well-delineated plaques with silvery scales that are usually on the extensor surfaces and scalp. "Generalized pustular psoriasis (GPP) is a rare but severe variant of psoriasis, and the levels of HMGB1 in both the skin and serum are significantly greater in patients with GPP than in those with PV and healthy controls." (PMID 40308590, 2025). "Previous studies have confirmed the crosstalk between KC-specific HMGB1-associated secretion and γδT cells in psoriasis." (PMID 40308590, 2025). "Several DAMP molecules, including high mobility group box 1 (HMGB1), uric acid, heat shock proteins (HSPs), ATP, the S100A family, and self-DNA, have been implicated in psoriasis pathology." (PMID 38255845, 2024). "Overall, HMGB1 is an important DAMP in the pathogenesis of psoriasis and a promising diagnostic and therapeutic target." (PMID 38255845, 2024). "Increased circulating and lesional HMGB1 is associated with psoriasis pathogenesis, supporting the potential role of these lytic cell death programmes in exacerbating inflammation in psoriasis." (PMID 35929827, 2022). "In recent years, increasing evidence suggests that HMGB1 is closely linked to psoriasis." (PMID 38255845, 2024). "Moreover, the systemic treatment of psoriasis reduces the expression of HMGB1, which strongly suggests its involvement in the underlying mechanisms leading to the development of psoriasis." (PMID 38666958, 2024). "Furthermore, as demonstrated in confocal fluorescence, HMGB1 co-localizes with keratins 1 and 10, molecules implicated in the pathogenesis of psoriasis, as these keratins are the markers of the early differentiation of keratinocytes." (PMID 38666958, 2024). "A recent study demonstrated that HMGB1 can promote Th17 cell differentiation from PBMCs derived from psoriasis patients and can increase the production of its effective cytokine IL‐17A in a dose-dependent manner." (PMID 40308590, 2025). "Increased levels of HMGB1 and increased numbers of HMGB1-secreting cells have been identified in skin lesions, including in vitiligo, psoriasis, atopic dermatitis, and pemphigus." (PMID 40308590, 2025). "Increased expression levels of cytoplasmic HMGB1 have been observed in both epidermal keratinocytes and dermal infiltrating immune cells in AD patients compared with healthy controls and those with psoriasis." (PMID 40308590, 2025). "Similar to the abundant cytoplasmic expression of HMGB1 in the lesional skin of psoriasis patients, IMQ‐induced psoriatic mice presented high HMGB1 cytoplasmic levels." (PMID 38414294, 2024). "HMGB1 can contribute to the pathogenesis of psoriasis by regulating Th17 cell differentiation through HMGB1‐TLR4‐IL‐23‐RORγt pathway, then promotes IL‐17A production and aggravates inflammation process." (PMID 38414294, 2024). "Wild‐type mice intradermally injection with rHMGB1 resulted in epidermal thickening; moreover, administration of HMGB1 into IMQ‐induced lesional skin can further worsen the severity of psoriasis‐like inflammation." (PMID 38414294, 2024). "Second, although HMGB1 has the potential to promote Th17 cell differentiation and induce IL‐17 expression in PBMCs of psoriasis patients by IL‐23 and TLR4 signaling pathways, more detailed mechanisms need to be explored and explained." (PMID 38414294, 2024). "The role of HMGB1 in psoriasis has been extensively studied, and its potential as a therapeutic target has been demonstrated in various preclinical studies." (PMID 38255845, 2024). "For instance, researchers have detected a significant elevation of serum HMGB1 levels in psoriasis patients compared to healthy individuals, with levels being closely related to disease severity." (PMID 38255845, 2024). "HMGB1 knockdown or inhibition using antibodies or small molecules have shown significant improvements in psoriasis symptoms in animal models." (PMID 38255845, 2024).
psoriasis (continued). "In this study, we first confirmed that HMGB1 was significantly increased in the peripheral circulation of psoriasis patients, which is consistent with previous reports." (PMID 38414294, 2024). "The described association between HMGB1 and vascular patterns provides an important correlation between HMGB1 levels and the severity of psoriasis, as the increase in the number of vascular patterns reflected the psoriasis severity." (PMID 38666958, 2024). "Our study demonstrates that HMGB1 can contribute to the pathogenesis of psoriasis by regulating Th17 cell differentiation through the HMGB1‐TLR4‐IL‐23‐RORγt pathway, then promote IL‐17A production and aggravate inflammation process." (PMID 38414294, 2024). "HMGB1 has been poorly studied in the field of PsA, but high levels have been found in serum and SF of patients with RA and with psoriasis." (PMID 36508130, 2023). "In inflammatory skin diseases, such as AD and psoriasis, HMGB1 acts as an endogenous danger signal that reacts with receptors, such as RAGE and Toll-like receptors (TLRs), to stimulate cytokine production." (PMID 37569742, 2023). "In psoriasis, HMGB1 can be released from keratinocytes, which potentiates the production and secretion of IL-18 by keratinocytes through an autocrine mechanism." (PMID 35075118, 2022). "Several studies have considered its role in the pathogenesis of psoriasis, and for this reason we decided to focus on the role of HMGB1 in this skin disease." (PMID 35053208, 2021). "Second, initial data have demonstrated that blocking HMGB1 is effective in ameliorating psoriasis similar to blocking some other alarmins (e.g., IL-33) in other chronic inflammatory skin diseases (e.g., atopic dermatitis)." (PMID 35053208, 2021). "Recently, HMGB1 has been shown to be secreted extracellularly by an autophagy-based unconventional mechanism in psoriasis by keratinocytes." (PMID 34134693, 2021). "The discovery of the relationship between HMGB1, psoriasis and chronic inflammation is arousing much interest." (PMID 35053208, 2021). "Elevated serum levels of HMGB1 have been found in patients with psoriasis, which are significantly decreased after treatment." (PMID 28769106, 2017). "Studies haves indicated that HMGB1 acts as a proinflammatory cytokine and is involved in the pathogenesis of psoriasis." (PMID 28769106, 2017). "It has been shown that HMGB1 levels are increased in the serum of patients affected by severe psoriasis." (PMID 29156622, 2017). "The keratinocytes in the skin lesions of psoriasis model mice showed increased HMGB1 expression." (PMID 38892253, 2024). "Peripheral blood mononuclear cells were acquired from 10 severe psoriasis patients and administrated by different concentrations of recombinant‐HMGB1 (rHMGB1) to detect the Th17 cell percentage, mRNA and protein levels of TLR4, IL‐23, IL‐17A and retinoid‐related orphan receptor γt (RORγt)." (PMID 38414294, 2024). "This highlights HMGB1 as a potential target for psoriasis treatment in keratinocytes." (PMID 38892253, 2024). "In the present study, we confirmed that both HMGB1 and TLR4 serum levels were positively correlated with IL‐23 in psoriasis and rHMGB1 can dose‐dependently increase its expression levels, further indicating the regulatory effect of HMGB1 on Th17 cell differentiation." (PMID 38414294, 2024). "In addition, the expression of HMGB1 in the lesion sites of psoriasis patients was also significantly increased compared with healthy people." (PMID 38255845, 2024). "Additionally, treatment with the HMGB1 inhibitor glycyrrhizin alleviated the condition of IMQ psoriasis mice." (PMID 38255845, 2024). "Furthermore, both necroptosis and ferroptosis in keratinocytes have been implicated in psoriasis and IMQ-induced psoriasis-like dermatitis, through the release of inflammatory cytokines such as S100A8, S100A9, HMGB1, IL-33, IL-1β, and IL-6." (PMID 38429278, 2024).